DUSP8 (dual specificity phosphatase 8)
Description:
Has phosphatase activity with synthetic phosphatase substrates and negatively regulates mitogen-activated protein kinase activity, presumably by catalysing their dephosphorylation. Expected to display protein phosphatase activity toward phosphotyrosine, phosphoserine and phosphothreonine residues.
Synonyms: C11orf81; HVH-5; HB5; FLJ42958; HVH8
Tractability: No criterion of Open Targets' tractability assessment is met for any kind of drug.
Gene: Protein-coding gene on chromosome 11 (1,554,051 to 1,573,076, reverse strand). Ensembl gene ENSG00000184545.
Subcellular location: Cytoplasm; Nucleus
Subcellular location (Human Protein Atlas): Cytosol
Pathways (Reactome):
Signal Transduction: Negative regulation of MAPK pathway; RAF-independent MAPK1/3 activation
Disease: Signaling by MAPK mutants
Gene Ontology:
Molecular function: protein binding; MAP kinase tyrosine phosphatase activity; MAP kinase tyrosine/serine/threonine phosphatase activity; phosphatase activity; protein tyrosine/threonine phosphatase activity; phosphoprotein phosphatase activity; protein serine/threonine phosphatase activity; protein tyrosine phosphatase activity
Biological process: dephosphorylation
Cellular component: cytoplasm; nucleus
Genetic constraint (gnomAD): Loss-of-function variants: 13 observed, 25.42 expected, observed/expected ratio (o/e) 0.51, 90% interval 0.33 to 0.81. The synonymous counts are far from expectation, so gnomAD's model fits this gene poorly and the ratio says little. Missense variants: 623 observed, 599.38 expected, observed/expected ratio (o/e) 1.04, 90% interval 0.97 to 1.11. Synonymous variants: 391 observed, 275.62 expected, observed/expected ratio (o/e) 1.42, 90% interval 1.3 to 1.54.
Homologues: Orthologues: pig DUSP8 (91% identical), mouse Dusp8 (89% identical), rat Dusp8 (88% identical), guinea pig DUSP8 (82% identical), macaque DUSP8 (82% identical), dog DUSP8 (78% identical), zebrafish dusp8a (56% identical). Paralogues in human: DUSP16 (47% identical), SSH2 (19% identical), SSH1 (19% identical), DUSP4 (18% identical), DUSP1 (18% identical), DUSP10 (18% identical), STYXL2 (18% identical), DUSP7 (17% identical), DUSP6 (17% identical), DUSP5 (17% identical), DUSP9 (16% identical), SSH3 (16% identical), and 19 more.
Diseases named in the same sentence as DUSP8 in open-access papers:
DUSP8 is named in the same sentence as 52 diseases in open-access papers, as found by Europe PMC text mining. Sharing a sentence is not in itself a finding about the gene and the disease. The quoted sentences say what the papers report.
breast carcinoma (5 papers, 2019 to 2024). "Surprisingly, analyzing DUSP8/hVH-5 transcripts in mammary carcinoma cell lines discovered a sequence with 88% similarity to hVH-5 transcripts." (PMID 31467668, 2019). "In the analysis for RFS, differential expression of ZNF611, ZNF304, RIPK1, DUSP8, TNFRSF21 and HRAS genes was associated with outcome for breast cancer patients who received radiotherapy." (PMID 30938061, 2019). "Previous studies reported that DUSPs contribute to EMT in breast cancer and glioblastoma, suggesting that DUSP8 may also play a role in these processes." (PMID 38396293, 2024). "Consistently, our proteomic results showed the suppression of critical proteins in the PI3K-mediated AKT-pathway, such as PP2A, DUSP8, and ARID1A, which were simultaneously overexpressed in breast cancer cells treated with combined MPSE and IR." (PMID 34217266, 2021).
colorectal carcinoma (3 papers, 2020 to 2024). A malignant epithelial neoplasm that arises from the colon or rectum and invades through the muscularis mucosa into the submucosa. "Inhibition of ILK/AKT decreases miR-21 in vestibular schwannoma and meningioma cells, and targeting miR-21 with antisense oligonucleotides (ASOs) inhibits growth and metastasis via upregulation of DUSP8 in colorectal carcinoma." (PMID 32260415, 2020).
Insulin resistance (3 papers, 2021 to 2023). Increased resistance towards insulin, that is, diminished effectiveness of insulin in reducing blood glucose levels. "The DUSP8 polymorphism rs2334499 was found to be related to hypothalamic insulin resistance in men, whereas DUSP8 has been described as a gatekeeper for systemic glucose tolerance and hypothalamic insulin sensitivity." (PMID 37402464, 2023). "Taken together, human carriers of the minor allele of the DUSP8 SNP rs2334499, which has previously been linked to T2D risk, hypothalamic insulin resistance and to a smaller hippocampal subiculum and CA4 layer volume, show a preference for sweet high caloric food compared to major allele carriers." (PMID 33131190, 2021). "Consistent with that still unexplored assumption, we found hypothalamic insulin resistance and systemic glucose intolerance in high‐fat diet‐fed Dusp8 KO mice." (PMID 33131190, 2021). "Next, Dusp8 overexpression in the mediobasal hypothalamus, using an adeno‐associated virus vector, reversed the HFD‐induced insulin resistance in Dusp8‐KO mice." (PMID 33943029, 2021). "In contrast, under high‐fat diet (HFD) feeding conditions, glucose tolerance and insulin resistance were exacerbated with no alteration of either insulin secretory capacity or body weight in male, but not in female, Dusp8‐KO mice." (PMID 33943029, 2021). "Given that both Dusp8 expression and JNK phosphorylation in the hypothalamus are reportedly upregulated in obesity, hypothalamic Dusp8 expression might be involved in a compensatory response to maintain HPA axis integrity, thereby preventing further exacerbation of insulin resistance." (PMID 33943029, 2021).
Obesity (3 papers, 2015 to 2024). Accumulation of substantial excess body fat. "In the metabolic homeostasis or cardiovascular system, DUSP8 could regulate the resistance to diet-induced obesity or cardiac ventricular remodeling by altering ERK1/2 signaling pathway." (PMID 38765936, 2024). "In summary, DUSP8, a type 2 diabetes risk gene, might be a novel gatekeeper that functions against deleterious metabolic effects induced by JNK activation in obesity." (PMID 33943029, 2021).
type 2 diabetes (3 papers, 2021 to 2022). "The increased preference for sweet high caloric food in Dusp8 minor allele adds to earlier work on the association of SNP rs2334499 minor allele with the overall type 2 diabetes risk or the increased hypothalamic insulin resistance." (PMID 33131190, 2021). "Dusp8 is the first GWAS‐identified gene that is predominantly expressed in the brain and has previously been linked with the development of diabetes type 2 in humans." (PMID 33131190, 2021). "A large‐scale genome‐wide association study and Metabochip meta‐analysis showed minor allele carriers of the DUSP8 single‐nucleotide polymorphism rs2334499 to be moderately associated with the risk of type 2 diabetes only in men." (PMID 33943029, 2021). "Type 2 diabetes risk is substantially increased by DUSP8 expression in individuals." (PMID 35889263, 2022). "Thus, details of the complexity of the association between type 2 diabetes susceptibility and DUSP8 polymorphism await future research." (PMID 33943029, 2021). "Further research is required to untangle the complex roles of proposed hypothalamic DUSP8‐JNK signaling in glucose homeostasis and, ultimately, thereby clarify the mechanism linking DUSP8 polymorphism with development of type 2 diabetes in humans." (PMID 33943029, 2021). "Consistently, Dusp8 in the infundibular nuclei of type 2 diabetes patients was shown to be significantly increased, as compared with non‐diabetic control individuals in the Netherlands Brain Bank." (PMID 33943029, 2021).
allergic disease (2 papers, 2023 to 2026). An immune response that occurs following re-exposure to an innocuous antigen, and that requires the presence of existing antibodies against that antigen. "Nevertheless, we cannot rule the possibility that the DUSP8–Pur-α axis may also regulate other allergy-associated cytokines directly or indirectly." (PMID 37909329, 2023). "Taken together, our findings suggest that DUSP8 is a T cell biomarker and potential therapeutic target for IL-9-mediated allergic diseases." (PMID 37909329, 2023). "An exciting finding in this report is that DUSP8 plays a critical role in Th9-mediated allergic diseases." (PMID 37909329, 2023). "Besides autoimmune diseases, reduction of DUSP1, DUSP2, and DUSP14, as well as induction of DUSP8 contribute to the pathogenesis of allergic diseases." (PMID 42087139, 2026). "To study whether the DUSP8–Pur-α–IL-9 axis contributes to other human allergic diseases, we further enrolled people with atopic dermatitis (AD)." (PMID 37909329, 2023). "Our findings and the database information support that DUSP8 is a key activator of IL-9 production and may be involved in human allergic diseases." (PMID 37909329, 2023).
Anxiety (2 papers, 2019 to 2021). Intense feelings of nervousness, tension, or panic often arise in response to interpersonal stresses. "Consistent with the human data, we found decreased hippocampus mass and perturbed anxiety, locomotion, and spatial cognition behaviors in mice with global Dusp8 deficiency." (PMID 33131190, 2021). "Recently, we already reported increased locomotion, and further revealed higher anxiety levels and impaired spatial cognition in mice deficient for Dusp8." (PMID 33131190, 2021). "Our behavioral assessment of Dusp8 WT and KO mice revealed mildly impaired spatial memory formation and visual performance, consistently higher locomotor activity in a variety of tests, and increased anxiety in Dusp8 deficient mice." (PMID 31862894, 2019). "Taken together, we found increased anxiety and hyperactivity as well as mildly, but significantly decreased spatial memory performance, visual performance and decreased hippocampal volume and mass in mice deficient for Dusp8." (PMID 31862894, 2019). "We next aimed to address in an Open Field Test, whether Dusp8 deficiency can affect anxiety behavior in a novel environment." (PMID 31862894, 2019). "Overall, our data indicate increased anxiety levels and locomotor activity in male Dusp8 deficient mice that are independent from a social context whereas Dusp8 female mice show a tendency to an increased locomotor activity but decreased vertical investigation." (PMID 31862894, 2019). "We here expand our earlier work that showed a role for the MAPK‐specific Dusp8 as gatekeeper for insulin resistance, cognition, and anxiety behavior in mice." (PMID 33131190, 2021). "Male Dusp8 KO mice show more pronounced anxiety relative to their WT littermates compared to female mice, where we see only a trend for anxiety in KO compared to WT mice." (PMID 31862894, 2019). "Prompted by our finding of mildly increased anxiety in Dusp8 KO mice, we next investigated the sensorimotor gating of Dusp8 KO mice by testing their startle response to an acoustic stimulus." (PMID 31862894, 2019). "We found higher anxiety levels in male Dusp8 KO mice and higher locomotor activity in male and female Dusp8 KO mice, which resonates with a previous report that showed elevated spontaneous behavior patterns in mice subjected to surgical hippocampus lesions." (PMID 31862894, 2019). "Only modest differences in phenotypes in the female and male Dusp8 KO mice nonetheless make it more likely that common mechanistic underpinnings exist that drive anxiety behavior and locomotion in male and female Dusp8 KO mice." (PMID 31862894, 2019). "Addressing these questions using Dusp8 WT and KO mouse littermates, we found that KOs suffered from mildly impaired spatial learning, increased locomotor activity and elevated anxiety." (PMID 31862894, 2019). "Prompted by the high expression of Dusp8 in the limbic system and especially the hippocampus, we focused our studies on evaluating the impact of Dusp8 ablation on cognitive functions, i.e. spatial and reverse task learning and memory performance, and on anxiety behavior." (PMID 31862894, 2019). "Future studies should interrogate the role of Dusp8 as regulator of visual performance and eyesight, and should further assess whether these effects are interlinked with deficits in cognitive behaviors and anxiety control." (PMID 31862894, 2019).
autoimmune disease (2 papers, 2023 to 2026). A disorder resulting from loss of function or tissue destruction of an organ or multiple organs, arising from humoral or cellular immune responses of the individual to their own tissue constituents. "It would be valuable to explore whether DUSP8 and Pur-α also play an important role in the pathogenesis of autoimmune diseases." (PMID 37909329, 2023).
colon cancer (2 papers, 2021 to 2024). "As the potential ability to dephosphorylate proteins, several DUSPs have been shown to play critical roles in human cancers, such as DUSP2 in colon cancer, DUSP6 in lung cancer, and DUSP8 in hepatocellular carcinoma." (PMID 33718185, 2021).
diabetes (2 papers, 2021). "Diabetes‐risk allele carriers of DUSP8 SNP rs2334499 preferred sweet high caloric food compared to the major allele carriers, rating scores for savory food remained comparable between groups." (PMID 33131190, 2021). "We further aimed to investigate the link between the human DUSP8 diabetes‐risk variant and the preference for sweet high caloric versus savory high caloric foods." (PMID 33131190, 2021). "Human carriers of DUSP8 diabetes‐risk SNP rs2334499 preferred sweet high caloric food compared to the major allele carriers." (PMID 33131190, 2021). "First, it is still unclear how DUSP8 polymorphism affects the role of hypothalamic DUSP8‐JNK signaling in glucose metabolism, leading to diabetes development." (PMID 33943029, 2021). "Dusp8 is reported to be highly expressed in the adult human brain, but whether or how DUSP8 participates in diabetes development has not been clarified." (PMID 33943029, 2021).
heart failure (2 papers, 2019). Inability of the heart to pump blood at an adequate rate to meet tissue metabolic requirements. "For example, in heart failure, DUSP8 repressed ventricular remodelling and disease susceptibility." (PMID 31400088, 2019). "In contrast, overexpression of DUSP8 led to decreased phosphorylation of all MAPKs studied, ventricular dilatation and greater propensity for heart failure." (PMID 31467668, 2019). "This study suggested that DUSP8 regulated the dynamics of cardiac MAPKs signaling pathway, which directly affected ventricular remodeling and heart failure propensity." (PMID 31467668, 2019).
lung carcinoma (2 papers, 2021 to 2024). "In this study, we found that DUSP8 expression in samples from patients with lung cancer correlates with OS, particularly with a devastating reduction in advanced LUAD stage 3 male patients, while the gender disparity is favorable." (PMID 38396293, 2024). "We also analyzed the post-transcriptional regulation of DUSP8 via miR-147b and the oncogenic potential of this miRNA using in vitro and in vivo models to determine its biological function in lung cancer progression." (PMID 38396293, 2024). "In conclusion, our results demonstrate strong lung cancer suppressive properties of DUSP8 in vitro and in vivo, and a corresponding supportive role of miR-147b as an inhibitor of DUSP8 expression in lung cancer progression." (PMID 38396293, 2024). "In this study, we examined the functional impact of DUSP8 in lung cancer progression using in vitro and in vivo models." (PMID 38396293, 2024). "This study investigated the role of DUSP8 in lung cancer progression and its regulation by miR-147b, with focus on MAPK signaling." (PMID 38396293, 2024). "Further, activation of JNK was reduced in the subcutaneous DUSP8-overexpressing tumor tissues, supporting the notion that DUSP8 may be important in lung cancer progression via regulation of JNK MAPK signaling." (PMID 38396293, 2024). "To address the question of how DUSP8 is downregulated in lung cancer, we considered that post-transcriptional regulation via microRNAs may be one of many ways." (PMID 38396293, 2024). "The link between DUSP8 and miR-147b may provide novel approaches for the treatment of lung cancer." (PMID 38396293, 2024). "Due to the suppression of DUSP8 by miR-147b and the inhibition of JNK activation, we observed a significant decrease in apoptosis in lung cancer cell lines." (PMID 38396293, 2024).
melanoma (2 papers, 2022 to 2024). A malignant, usually aggressive tumor composed of atypical, neoplastic melanocytes. "We transfected MAPKi-resistant MRA5 and MAPKi-sensitive MRA6 metastatic melanoma cells with control or DUSP1 or DUSP8 siRNA and then treated the cells with 10 μM BRAFi or MEKi alone or in combination." (PMID 35999349, 2022). "Next, we investigated the effect of DUSP1 and DUSP8 KD on MAPKi sensitivity of melanoma cells." (PMID 35999349, 2022). "A further analysis of MAPK regulatory genes showed that mRNAs for several DUSPs-DUSP1 DUSP5, DUSP8, DUSP10 and DUSP14-were upregulated in intrinsically MAPKi-resistant melanoma cell line." (PMID 35999349, 2022). "To understand the role of DUSPs in melanoma cell survival, we used siRNA-mediated knockdown (KD) of DUSP1 or DUSP8, employing MISSION® esiRNAs (Millipore Sigma), which are endoribonuclease prepared heterogeneous pools of siRNA that all target the same mRNA sequence." (PMID 35999349, 2022). "Notably, Singh and colleagues recently reported that melanoma cells are reliant on DUSP1 and DUSP8 expression for proliferation and that DUSP1 protein expression is reduced in MAPKi-sensitive and -resistant melanoma cells treated with BRAFi, consistent with the data reported here." (PMID 38300709, 2024).
ovarian carcinoma (2 papers, 2013 to 2020). A malignant neoplasm originating from the surface ovarian epithelium. "Overall, these observations suggest that ILK regulates the JNK/c-JUN pathway in cisplatin-resistant ovarian cancer via modulation of DUSP8, MARVELD3, PDCD4, MAPK8IP1, MAPK8IP2, and HIPK3." (PMID 32260415, 2020). "A similar example is DUSP8, a gene whose promoter methylation predicts clinical outcome of ovarian cancer and MAPKAPK2, which is known to regulate invasion of bladder cancer." (PMID 24391728, 2013).
alcohol dependence (1 paper, 2019). Physical and psychological dependence on alcohol. "However, there was not significant association between DUSP8 C712T polymorphism and alcohol dependence by using genotyping of analyzing functional of DUSP8 in 463 Southwestern Native Americans." (PMID 31467668, 2019). "And DUSP8 gene not only met the candidate criteria, but also played a crucial role in various pathways known to constitute pathophysiological mechanisms leading to the development of alcohol dependence, which was sequenced to identify polymorphisms that might be associated with disease." (PMID 31467668, 2019).